FCHO1 (FCH and mu domain containing endocytic adaptor 1)
Description:
Functions in an early step of clathrin-mediated endocytosis. Has both a membrane binding/bending activity and the ability to recruit proteins essential to the formation of functional clathrin-coated pits. May regulate Bmp signaling by regulating clathrin-mediated endocytosis of Bmp receptors. Involved in the regulation of T-cell poliferation and activation. Affects TCR clustering upon receptor triggering and modulates its internalization, playing a role in TCR-dependent T-cell activation.
Synonyms: KIAA0290; IMD76
Tractability: Antibody: UniProt places it where antibodies can reach, with high confidence; its Gene Ontology location is reachable by antibodies, with high confidence. PROTAC: ubiquitination databases record sites on it; its protein half-life has been measured.
Gene: Protein-coding gene on chromosome 19 (17,747,718 to 17,788,572, forward strand). Ensembl gene ENSG00000130475.
Subcellular location: Membrane, clathrin-coated pit
Subcellular location (Human Protein Atlas): Nucleoplasm; Cytosol
Pathways (Reactome):
Vesicle-mediated transport: Cargo recognition for clathrin-mediated endocytosis; Clathrin-mediated endocytosis
Gene Ontology:
Molecular function: AP-2 adaptor complex binding; protein binding
Biological process: clathrin coat assembly; clathrin-dependent endocytosis; positive regulation of T cell activation; T cell receptor signaling pathway
Cellular component: clathrin-coated pit; clathrin-coated vesicle; cytosol; nucleoplasm; plasma membrane; cytoplasm; postsynaptic endocytic zone
Genetic constraint (gnomAD): Loss-of-function variants: 43 observed, 111.05 expected, observed/expected ratio (o/e) 0.39, 90% interval 0.3 to 0.5. The upper end of that interval is the gene's LOEUF score, 0.5, which puts it in group 2 of 6, group 1 being the genes least tolerant of losing a copy. Missense variants: 1,041 observed, 1,198.5 expected, observed/expected ratio (o/e) 0.87, 90% interval 0.82 to 0.91. Synonymous variants: 480 observed, 484.14 expected, observed/expected ratio (o/e) 0.99, 90% interval 0.92 to 1.07.
Gene-disease validity (ClinGen):
ClinGen rates the evidence that FCHO1 causes each of these diseases.
immunodeficiency 76 (autosomal recessive): Definitive. An autosomal recessive primary immunologic disorder characterized by onset of recurrent bacterial, viral, and fungal infections in early childhood.
Homologues: Orthologues: chimpanzee FCHO1 (96% identical), macaque FCHO1 (93% identical), pig FCHO1 (93% identical), dog FCHO1 (93% identical), mouse Fcho1 (86% identical), rat Fcho1 (85% identical), guinea pig FCHO1 (83% identical), zebrafish fcho1 (51% identical), tropical clawed frog fcho1 (51% identical), Drosophila melanogaster CG8176 (36% identical), Caenorhabditis elegans fcho-1 (25% identical). Paralogues in human: FCHO2 (44% identical), SGIP1 (27% identical), PSTPIP1 (10% identical), PSTPIP2 (8% identical), GAS7 (7% identical).
Diseases named in the same sentence as FCHO1 in open-access papers:
FCHO1 is named in the same sentence as 15 diseases in open-access papers, as found by Europe PMC text mining. Sharing a sentence is not in itself a finding about the gene and the disease. The quoted sentences say what the papers report.
lung carcinoma (2 papers, 2022 to 2024). "In addition to its role in benign PTs, FCHO1, which regulates cell division, participates in tumorigenesis in leukemia and solid tumors such as lung cancer." (PMID 36271373, 2022).
combined immunodeficiency (1 paper, 2020). A broad classification of inherited disorders presenting at birth that affect both the cell-mediated and humoral aspects of the immune response. "Here, we identify autosomal recessive FCHO1 deficiency as a human genetic defect associated with combined immunodeficiency (CID)." (PMID 32098969, 2020).
coronary artery disease (1 paper, 2023). "The C allele of the SNP was associated with attenuated chromatin accessibility, reduced FCHO1 expression and increased risk of developing a complex inflammatory disease, coronary artery disease." (PMID 37805492, 2023). "Our results suggest that re-activation of FCHO1 or its associated enhancer may be a potential therapeutic target for coronary artery disease." (PMID 37805492, 2023).
Guillain-Barre syndrome (1 paper, 2024). A spectrum of rare post-infectious neuropathies that usually occur in otherwise healthy patients. "Deficiency of FCHO1 has been shown to be associated with both IBD and Guillain Barré syndrome." (PMID 38741190, 2024).
lymphopenia (1 paper, 2020). Reduction in the number of lymphocytes. "Here, the authors report homozygous FCHO1 mutations in individuals with variable T and B cell lymphopenia, which are associated with loss-of-function of FCHO1 and impaired formation of clathrin-coated pits in T cells." (PMID 32098969, 2020).
Obesity (1 paper, 2021). Accumulation of substantial excess body fat. "After being viewed as a candidate gene for energy homeostasis and a determinant of obesity-related traits, SGIP1 was identified as an ortholog of FCHo1/2 and thus was thought to play a role in CME." (PMID 35004694, 2021).
primary immunodeficiency disease (1 paper, 2022). "FCHO1, implicated in primary immunodeficiency disease, is a member of the Fer/CIP4 homology-Bin/amphiphysin/Rvs (F-BAR) protein family, which contains an F-BAR domain." (PMID 36271373, 2022).
Sepsis (1 paper, 2024). Sepsis is defined as life-threatening organ dysfunction caused by a dysregulated host response to infection. "Particularly, the significant downregulation of FCHO1 in sepsis patients who died at 28 days underscores its potential relevance to adverse clinical outcomes." (PMID 38167131, 2024). "Furthermore, compared to sepsis patients who survived at 28 days, we observed a significant downregulation of FCHO1 in sepsis patients who died at 28 days." (PMID 38167131, 2024).
T-cell immunodeficiency (1 paper, 2020). A broad classification of disorders that affect the cell-mediated aspect of the immune response. "Given the central role of FCHO1 for the formation of clathrin-coated pits and endocytosis it is surprising that FCHO1 deficiency results in T-cell immunodeficiency rather than more global defects of development." (PMID 32098969, 2020).
T-cell lymphoma (1 paper, 2020). "To test this, we took advantage of the CD4-positive human Jurkat T-cell lymphoma line in which we deleted the endogenous FCHO1 gene using CRISPR/Cas9 gene editing." (PMID 32098969, 2020).
infection (1 paper, 2020). The state of being infected such as from the introduction of a foreign agent such as serum, vaccine, antigenic substance or organism. "Jurkat wt and FCHO1 ko clones were challenged with different multiplicities of infection of either VSV-G HIV-1ΔEnv (BlaM-Vpr) or VSV-G HIV-1ΔEnv." (PMID 32098969, 2020). "Taken together, FCHO1 deficiency in Jurkat T cells does not functionally impair CME in the context of VSV-G-mediated entry and infection of a lentivirus pseudotype." (PMID 32098969, 2020). "FCHO1-deficient Jurkat T clones displayed a susceptibility to VSV-G pseudotyped HIV-1, monitored by both virion fusion and productive infection, that was indistinguishable from that of wt clones." (PMID 32098969, 2020).
FCHO1 also shares sentences with these, for which no sentence is quoted: Autoimmunity (1 paper); leukemia (1); T-cell deficiency (1); virus infection (1).